CRP (C-reactive protein)
Diseases named in the same sentence as CRP in open-access papers (continued):
Sharing a sentence is not in itself a finding about the gene and the disease.
infection (continued). "CRP is an acute-phase reactant synthesized by the liver in response to inflammatory cytokines (primarily interleukin 6) generated by white blood cells reacting to microbial pyrogens, with a cut-off between 0.5 and 1 mg/dL in most studies about late-onset infections." (PMID 38535886, 2024). "The correlation of higher C-reactive protein levels at the time of diagnosis with elevated anti-spike IgG blood levels one year post diagnosis may also reflect a relationship between the severity of the infection and the strength of the serologic response." (PMID 39204223, 2024). "Thus, we cannot recommend ruling out the possibility of nonunion-caused low-grade infection preoperatively by a sole consideration of CRP values or WBC." (PMID 38592249, 2024). "Therefore, after using an immunosuppressive monoclonal antibody, neither PCT nor CRP were observed to be effective as trustworthy diagnostic techniques in the context of possible infection." (PMID 39685604, 2024). "In addition, synovial fluid contains infectious biomarkers, such as glucose, a low pH, high lactate concentrations, C-reactive protein, interleukins, interferon-γ, α-defensins, and cathelicidins, which may be useful for the diagnosis of infection." (PMID 38337382, 2024). "The elevated white blood cell count, and C-reactive protein may reflect infection and inflammation." (PMID 38756601, 2024). "As infection and inflammation are associated with SPTB3, an acute phase response may be activated already in early pregnancy, leading to increased concentrations of maternal serum AAT and CRP." (PMID 38734716, 2024). "However, due to the limited studies available for comparison, it is imperative that more large-scale prospective investigations are required to compare the diagnostic accuracy of PCT and CRP in differentiating infections among non-neutropenic cancer patients." (PMID 38438974, 2024). "Therefore, CRP is another indicator for early diagnosis of infection besides PCT." (PMID 38356842, 2024). "Therefore, the combination of IL-6 and CRP better marker than alone IL-6 for low-grade infection." (PMID 39493345, 2024). "CRP is an immune regulator, rather than only a marker for inflammation or infection, so a potential causal role for CRP may exist in inflammatory musculoskeletal conditions." (PMID 39006441, 2024). "Chen’s study revealed that levels of PCT, CRP, HCT, and BUN within 48 hours of admission are independent risk factors for infective pancreatic necrosis, and their combination might more accurately predict secondary necrotizing pancreatitis with infection." (PMID 38787912, 2024). "However, infection, nutritional status, and metabolic health all impact CRP." (PMID 38443857, 2024). "This could be attributed to the pleiotropic inflammatory effects of CRP, i.e., defense against infection but also a pro-atherosclerotic impact: younger patients, with a lower cardiovascular risk, may benefit from the former, while the latter may lead to vascular complications in older patients." (PMID 39575025, 2024). "Due to the vast reference ranges of routine blood indicators and CRP in some patients, misinterpretation may occur if baseline values are within the middle-lower reference ranges and rise to the upper limit of the reference ranges after pathogen infection." (PMID 38306568, 2024). "In addition to the standard administration criteria of anticancer drugs, checking patients’ infection-related condition, defined by a body temperature ≥ 37.5 °C or elevated CRP or WBC from baseline, before mixing by the pharmacist is useful for reducing anticancer drug wastage after preparation." (PMID 36650580, 2023). "HIV infection can cause elevated CRP values, and CRP could potentially act as prognostic marker of Immune Reconstitution Inflammatory Syndrome (IRIS), which may occur after various related infections." (PMID 37873776, 2023).
infection (continued). "However, the post hoc analysis demonstrated that serum CRP change after PEG implantation could predict subsequent infection, which might be beneficial for clinical practice." (PMID 37189057, 2023). "This implies that CRP may be more practically applicable for ruling out infection." (PMID 37868444, 2023). "CRP is the most frequent marker of inflammation, but its biggest disadvantage is its low specificity due to the fact it is increased in all inflammatory processes, even when they are not caused by the infection." (PMID 36769843, 2023). "CRP, synthesized primarily by the liver in response to inflammatory cytokines (interleukin-6, interleukin-8, and tumor necrosis factor-α), is one of the most frequently used inflammatory markers in clinical practice and is released following either an infection, inflammation, or tissue damage." (PMID 37286951, 2023). "In addition, a secondary and unspecific CRP elevation in absence of an underlining infection, and pronounced after prolonged perfusion for more than 60 min." (PMID 36631814, 2023). "Higher CRP values may indicate a more aggressive and extensive infection." (PMID 37640802, 2023). "However, CRP can accurately predict infection in patients with impaired renal function." (PMID 36832265, 2023). "Furthermore, 7/14 (50%) subjects had both a clinical picture and normal CRP values; the other 5/14 (35.71%) presented a clinical picture not suggestive of an infection associated with abnormal CRP levels." (PMID 37237840, 2023). "In addition, the identification of the CRP patterns could increase our ability to identify patients with ICU-acquired infection." (PMID 37834754, 2023). "As demonstrations of our approach, we developed sensors for two human biomarkers—monomeric C-reactive protein and interleukin-32γ protein—that have been previously used as serum-accessible proxies for cardiovascular disease, pro-inflammatory conditions, and pathogen infection." (PMID 37105971, 2023). "In conclusion, we have shown that the combined use of routine laboratory tests such as NLR and CRP may be used to predict infection in maintenance hemodialysis patients, and can help in their early management to reduce the incidence of subsequent complications." (PMID 37016028, 2023). "Indeed, the rise in CRP starts at 4–6 h and peaks at 36 h after infection." (PMID 38137490, 2023). "In addition, when low albumin accompanies high CRP, it can be an indicator of infection." (PMID 37308964, 2023). "We observed that certain HIPEC protocols can suppress the WBC response to infection and may cause secondary and unspecific CRP elevations without underlining infection." (PMID 36631814, 2023). "Moreover, several studies have added to the current literature, noting that serum CRP concentrations may predict various post-surgery infections [1030,1031]." (PMID 37873776, 2023). "CRP rises rapidly during the initial stages of infection, with elevated values correlating positively with the severity of the infection or inflammation, and can serve as a sensitive biomarker for many inflammatory diseases, such as infections and tissue damage." (PMID 37685276, 2023). "Thus, identifying severe infections based on CRP value appears sensible." (PMID 37314998, 2023). "However, a clinically relevant infection is a contraindication for elective heart surgery at our center, which was also represented by the low CRP levels measured at baseline measured by routine laboratory methods, suggesting that the overall preoperative inflammatory status of our patients was low." (PMID 38379859, 2023). "In addition to CRP, the host-response marker procalcitonin may be valuable in the etiology differentiation, and appears to be the earliest marker to appear during infection." (PMID 37107150, 2023). "Moreover, Hb and CRP whether at diagnosis or before infection were significantly different between the infected group and the non-infected group in N-DLBCL patients (P < 0.05)." (PMID 37864133, 2023).
infection (continued). "However, elevated inflammatory serological markers that are often linked to bacterial infection, such as elevated PCT and CRP, are not specific and can also occur without such infection." (PMID 37887248, 2023). "However, CRP is an essential test in clinical laboratories when infection is suspected." (PMID 37510151, 2023). "We compared multiple blood tests between cases and contemporary controls and none associated with prior infection, including C-reactive protein, white blood cell count, and conventional cardiac, kidney, liver, and thyroid function tests, accounting for multiple testing (P < 8 × 10−4)." (PMID 37414856, 2023). "In addition, by simultaneously measuring both WBC and CRP, it may aid in identifying the timing of infection, early determination of therapeutic effects, and assessing the severity of the disease." (PMID 37510151, 2023). "In addition, although preoperative ESR and CRP level are effective screening methods, occult infection may still be missed." (PMID 35813227, 2022). "Despite excluding patients with known inflammatory/suspected infection, we were unable to determine if the rise in CRP was due to new but occult infection, whether it was secondary to inflammation during STEMI or if it was due to a different concurrent inflammatory process in the patient." (PMID 35054095, 2022). "Secondly, CRP concentrations could have been affected by active infections." (PMID 34478414, 2022). "Moreover, serum CRP is prone to be influenced by other factors, such as infection." (PMID 36494477, 2022). "Even if this biomarker is not specific for UTIs, the baseline and dynamics of CRP’s serum levels represent an adequate tool for risk stratification and prognosis assessment of every admitted patient, regardless the etiology of infection or the resistance pattern." (PMID 35625192, 2022). "CRP, an acute phase protein produced by the liver in response to any infection or inflammation, has been studied extensively but its role in predicting severe infections in older adults remains unclear." (PMID 35255822, 2022). "The indicators of infection increased as follows: 4 patients had increased leucocytes (30.77%), 12 patients (92.3%) had increased neutrophils with a decreased percentage of lymphocytes, and all patients had increased C-reactive protein (CRP) and procalcitonin (PCT)." (PMID 35938720, 2022). "However, CRP increased at 12 hours after infection and peaked at 20-72 hours." (PMID 35633256, 2022). "In terms of circulating CRP, we cannot exclude that non-differential misclassification may have occurred in our analysis, since CRP was measured only at one time point pre-diagnostically, and this measurement may also have been affected by acute inflammatory response due to infection." (PMID 35739525, 2022). "In mammals, CRP could increase dramatically during injury, infection, and inflammation." (PMID 36009776, 2022). "CRP and IL-6 might serve as independent factors prewarning the severe infection occurrence." (PMID 35037900, 2022). "Although previous investigation reported moderate sensitivities and high specificities of CRP to detect persistent infection in patients with inflammatory arthritis, our analysis failed to exhibit any significant association between infection persistence and CRP in rheumatic patients." (PMID 36139954, 2022). "In addition, 2 patients had findings suggestive of inflammation secondary to infection due to their sudden increase in CRP levels at week 8 and their good response to antibacterial drugs, and were excluded from the subgroup evaluation of inflammation-related indicators." (PMID 35949598, 2022). "Furthermore, it was not possible to consider factors such as a recent history of surgery or infection, which could have temporarily increased hs-CRP levels." (PMID 36517526, 2022).
infection (continued). "Obvious clinical signs of infection such as redness, swelling, sinus tract formation and fever are rarely encountered in infections caused by these low-virulent microorganisms and especially in these cases, CRP should not be used alone to rule out a diagnosis of shoulder PJI." (PMID 33515325, 2022). "Moreover, the expression profiles and immunological roles of On-CRP during two common pathogenic bacteria, Streptococcus agalatiae (Gram-positive bacteria), and Aeromonas hydrophila (Gram-negative bacteria) infection were investigated." (PMID 36009776, 2022). "In febrile children where no infection was diagnosed (20.5%; 81/396), and whose actual cause of fever remained unknown, the CRP test was positive in 63.0% (51/81) of the cases and negative in 37.0% (30/81) of the children." (PMID 36536340, 2022). "The timing of CRP testing relative to the onset of infection may also influence CRP peak levels." (PMID 36517750, 2022). "The post-mortem CRP concentration (66.3 mg/L) and the presence of the same species of enterococci in the blood of the decedent as those seen in the intra-abdominal abscess indicate an endogenous infection and potential impairment of the patient’s immune system mechanisms." (PMID 35215147, 2022). "For example, secondary conditions, such as infections, might affect CRP levels." (PMID 35752767, 2022). "Also of note, among patients who opted for a surgical decompression procedure, we observed a significant improvement in the infection parameters and motor function at discharge, while in the instrumentation group, only the reduction in CRP levels reached statistical significance." (PMID 35536406, 2022). "Additionally, it correlated with indicators of infection and inflammation, such as CRP and WCC." (PMID 34344786, 2022). "CRP in pSLE is usually associated with seritis or infection rather than disease flares." (PMID 36371201, 2022). "Leukocytes and C-reactive protein have been shown to be reactive indicators of infection and inflammation, while platelets, eosinophils, and bilirubin are significantly altered during severe infection, which may be the reason for their exclusion from the model." (PMID 36081635, 2022). "Interestingly, the synopsis of calprotectin, CRP, WBC, PMN and the clinical signs of infection increased the diagnostic performance considerably in this study, which underlines the potential added value of calprotectin to existing PJI diagnostics in the setting of PFF." (PMID 36319727, 2022). "In addition, the characteristics of the new infection—especially at the beginning—highlighted the “weaknesses” of traditional biomarkers, such as procalcitonin and C-reactive protein, but also, d-dimer and cardiac enzymes, which were progressively used as “surrogates” for possible damage mechanisms." (PMID 35956159, 2022). "Total effect of infection on 12-month metabolomic and lipidomic measures (purple, circle points) and the estimated natural indirect effect component of these mediated by glycoprotein acetyls (GlycA) (orange, square points) or high-sensitivity C-reactive protein (hsCRP) (green, diamond points)." (PMID 35535496, 2022). "In addition, the CRP levels are elevated in various inflammatory conditions other than infection, as well as in invasion such as surgery and trauma, thus making it difficult to determine whether they indicate the presence of infection in clinical practice." (PMID 36494434, 2022). "CRP levels ≥231.3 mg/L (AUC=0.81, sensitivity=0.89, specificity=0.73) and ≥230 mg/L (AUC=0.82, sensitivity=0.83, specificity=0.71) at 3rd postoperative day were found to be the sensitive cutoff point for predicting infection at day 14 and 28 post-operative days respectively." (PMID 35991254, 2022).
infection (continued). "As C-reactive protein is part of a dynamic and continuous inflammatory process, a single CRP measurement, especially at low concentrations, may erroneously lead to a wrong classification of an infection as viral over bacterial and delay appropriate antibiotic treatment." (PMID 35897672, 2022). "In our study, patients with elevated CRP over 1.83 times were more likely to develop severe infections after receiving Tocilizumab, which suggested that we should pay more attention to the patients’ infection progression after administration of Tocilizumab and intervene as soon as possible." (PMID 35799791, 2022). "Because the presence of inflammation anywhere in the body can increase CRP levels, significant reductions in CRP induced by exercise and weight loss may be counter balanced by other factors that increase systemic CRP including infection, stress, and poor sleep." (PMID 34222367, 2021). "Therefore, the identification of participants whose CRP levels were influenced by infection or other acute conditions could be pivotal to better using DBS CRP to identify individuals with increased cardiovascular risk in this region." (PMID 34943129, 2021). "It is notable that elevation of just CRP or ESR may also imply the presence of infection." (PMID 33736624, 2021). "Factors and mechanisms involved in inflammation and infection are also involved in the pathogenesis of cardiovascular disease: macrophages are found in atherosclerotic plaques and inflammatory markers like high-sensitivity C-reactive protein (CRP) levels can predict coronary events." (PMID 33497395, 2021). "For example, if a description of the reason for elevated CRP was lacking, whether it was caused by disease activity or by accompanying infection, it had to be inferred by using other disease activity indices." (PMID 34575390, 2021). "Interestingly, during low-grade inflammation without infection, serum CRP levels between 1 and 10 mg/L were associated with an increased risk of cardiovascular disease." (PMID 34764364, 2021). "Regarding the laboratory inflammation markers, CRP (which is mainly expressed under transcriptional control of IL-6 with contribution of IL-1) was suggested to be appropriate, as it rises and declines rapidly following infection or tissue injury and its subsequent resolution." (PMID 34071813, 2021). "Due to the retrospective nature of this study, it cannot be finally determined whether AML patients with a higher CRP need more crystalloid fluids and FO is a largely unavoidable consequence or whether FO promotes infection and inflammation reflected by significantly higher CRP levels." (PMID 34304288, 2021). "As it might be expected, all parameters under assessment were significantly higher in patients with severe illness than in those with mild or moderate infection, although the patients in the latter group had some increased parameters as well, such as C-reactive protein." (PMID 34722035, 2021). "Indeed, the higher level of CRP was representative of more severe infection." (PMID 34573878, 2021). "Furthermore, the formation of biofilms in the chronic stage may affect the utility of ESR and CRP to evaluate infection." (PMID 34030692, 2021). "In addition, the use of biomarkers such as procalcitonin, C-reactive protein, or presepsin may be used to confirm the presence of an infection, since the combination of different tests may increase their positive predictive value." (PMID 34579693, 2021). "In the line of these findings, Chung and colleagues have described that serum procalcitonin level is not affected by IBD activity itself, although they may be affected by concomitant enteric infections and is more useful than CRP to distinguish infection stage from a flare-up of the disease." (PMID 34702217, 2021). "However, there were significant differences in the CRP levels, which may indicate that the severity of infection was greater in the PNA group than in the antibiotics alone group." (PMID 32677915, 2020).